MMP2 (matrix metallopeptidase 2)
Diseases named in the same sentence as MMP2 in open-access papers (continued):
Sharing a sentence is not in itself a finding about the gene and the disease.
breast cancer (continued). "Low TIMP-2 levels in the blood of breast carcinoma patients could indicate more activated MMP-2 and therefore higher usage of TIMP-2, or alternatively, the lower levels could be due to lower production of TIMP-2, leading to lesser inhibition of MMP-2 activity." (PMID 19662197, 2007). "Several MMPs, in particular the gelatinases MMP-2 and MMP-9, have been recently studied as prognostic factors in breast cancer, being associated with a poor outcome in various subsets of patients." (PMID 17848954, 2007). "Of the MMP-14/TIMP-2/MMP-2 complex, MMP-14 was the factor most significantly associated with the outcome of breast cancer and was an independent factor of poor overall survival when adjusted for clinical prognostic factors, but not for certain ancillary markers." (PMID 16776850, 2006). "First, though MMP-2 levels are increased in mouse mammary tumors, its expression is confined to the stroma, suggesting that increased MMP2 transcription after loss of the epithelium-specific MUC1 might reflect a shift towards a more mesenchymal phenotype." (PMID 16846534, 2006). "In breast cancer, the ratio of active to latent MMP-2 increases with tumor progression; MMP-2 may facilitate both angiogenesis and metastasis." (PMID 16846534, 2006). "However, since the THP-1 monocyte cell line differs in many respects from TAMs, further study is needed to assess the in vivo activities of monocyte cells and to determine if MMP-2 is upregulated by monocytes in the breast cancer microenvironment in vivo." (PMID 16168111, 2005). "Our qualitative analysis of the zymograms showed that the majority of the 80 sera samples from breast cancer patients displayed sharp bands of lysis corresponding to the proenzyme forms of MMP-2 and MMP-9, respectively, in contrast to the 22 control samples which showed less pronounced lytic bands." (PMID 15054465, 2004). "The present data shows for the first time that MMP-2 negativity could serve as a marker for distinctly favourable prognosis in breast carcinoma patients." (PMID 14520459, 2003). "Additionally, it could reduce the invasion and metastasis of MDA-MB-231 breast cancer cells by suppressing the expression of matrix metallopeptidase 2 (MMP-2) and matrix metallopeptidase 9 (MMP-9)." (PMID 38505423, 2024). "However, in the literature, in several studies focused on different disease conditions such as intrahepatic cholestatic of pregnancy, or breast cancer, Celastrol is shown to suppress MMP-2 and -9 activities, which is contrary to our current observation in AngII-induced AAA model." (PMID 37189351, 2023). "This suggests that mammary tumour-associated MMP-2 expression is not influenced by the lack of HPSE in MMTV-PyMTxHPSE−/− mice and a previously proposed compensatory mechanism of upregulated MMP expression may not exist in this model." (PMID 37297024, 2023). "Similarly, another study showed that high preoperative serum levels of MMP-2 were associated with shorter disease-free survival in patients with breast cancer in ER-negative, higher histologic grade, or higher nuclear grade breast cancers." (PMID 36741729, 2022). "Moreover, MT1-MMP participates in MMP2 activation affecting breast cancer cell invasiveness." (PMID 33809973, 2021). "Moreover, ZA inhibits the expression of MMP-2 to suppress breast cancer metastasis." (PMID 33143662, 2020). "Moreover, the progression of breast cancer is attributed to MMP-2,−7,−9,−10,−11,−13,−14, and−15." (PMID 33520928, 2020). "Brucine could inhibit the bone metastasis of breast cancer by regulating the expression of bone metastasis-related factors such as matrix metallopeptidase 2 (MMP-2), chemokine (C-X-C motif) receptor (CXCR4), receptor of NF-κB ligand (RANKL), and osteoclastogenesis inhibitory factor (OPG)." (PMID 32308621, 2020).
breast cancer (continued). "Immunohistochemical analysis of tumour sections showed that MMP‐2+ cells and Ki‐67+ cells were remarkably decreased in tumour tissues of mice after treatment of hinokiflavone, indicating that hinokiflavone inhibits not only proliferation but also metastasis of breast cancer cells." (PMID 32107809, 2020). "Therefore, CAPE-pNO2 against the growth and metastasis of breast cancer might be via restraining MMP-2, MMP-9, and VEGFA expression, and these proteins were associated with the EGFR/STAT3/Akt signaling pathway." (PMID 31214503, 2019). "In addition, the MMP-2 gene was transfected into another breast cancer cell line, MDA-MB-231." (PMID 31514467, 2019). "Twist1 could induce ECM remodeling by activating cancer-associated fibroblast to synthesize and secret high levels of ECM proteins, such as MMP2, which was proved to be related to tumor formation, metastasis, and responsible for high mortality breast and poor prognosis in breast cancer patients." (PMID 30819235, 2019). "To expose some molecular mechanisms by which Pax-5 could suppress breast cancer aggressive features, we performed RT-qPCR on molecular mediators of breast cancer malignancy such as: MMP2 and MMP9; vimentin and fibronectin following Pax-5 transfection of MB231 cells." (PMID 28076843, 2017). "In addition, vascular remodeling factors, including epiregulin, cyclooxygenase 2 (COX2), MMP1, and MMP2, can promote breast cancer lung metastasis through facilitating the release of tumor cells into the circulation system and breaching lung capillaries by circulating tumor cells." (PMID 28356139, 2017). "Moreover, R-cad was found to inhibit expression of MMP-1, MMP-2, and Cox-2 in mammary tumors." (PMID 27783992, 2016). "However, it is controversial whether MMP-2 positivity was relevant with worse OS in breast cancer patients." (PMID 26270045, 2015). "However, because IGFBP-2 could create a microenvironment that is more favorable to invasion and metastasis through the up-regulation of MMP-2, the adipocytes may become a new target to reduce the extent of breast cancer metastasis." (PMID 25747684, 2015). "We evaluated genetic variation in MMP1 (9 SNPs), MMP2 (8 SNPs), MMP3 (4 SNPs), and MMP9 (3 SNPs) and breast cancer risk among Hispanic (2111 cases, 2597 controls) and non-Hispanic white (NHW) (1481 cases, 1586 controls) women in the Breast Cancer Health Disparities Study." (PMID 23696797, 2013). "In contrast, LEF1 was able to regulate MMP-7 expression and activity in breast cancer cells, whereas another previous study showed that circulating MMP-2 and MMP-9 could be used to potentially classify patients into low risk, high risk, benign disease, and breast cancer." (PMID 24098538, 2013). "The αvβ3 integrin, which is overexpressed in certain breast cancers, can interact with and enhance the activation MMP-2 in melanoma cells to promote invasion, and a similar mechanism could benefit breast cancer cells which express the same combination of proteins." (PMID 22523705, 2012). "Immunohistochemical and statistical analysis found that MMP-2 and MMP-9 expressions are positively related to HER2 overexpression in the stromal cells of breast carcinoma, implicating that MMP-2 or MMP-9 may be a responsive gene of HER2 signaling in breast cancer metastasis." (PMID 19617202, 2011). "In addition, membrane ER can activate Src-MMP2/9-EGFR-MAPK pathway through Gαi protein in breast cancer cells, and activate MAPK-dependent endothelial nitric oxide synthase (eNOS) to increase NO production, contributing to the beneficial effects on cardiac cells." (PMID 21859479, 2011). "Furthermore, BER suppresses Akt and nuclear factor κB signaling by reducing the phosphorylation of c-Met and Akt, and inhibiting their downstream targets such as nuclear factor κB p-65, Bcl-2/Bax, osteopontin, VEGF, MMP-9 and MMP-2 on protein and/or mRNA levels in breast cancer cells." (PMID 19796390, 2009).
breast cancer (continued). "It has also been described that as breast cancer progresses, MMP-2 production increases during the early phases, whereas activation of MMP-9 occurs during the late cancerous stage, which could explain their different impact on prognosis in clinically detected invasive breast tumours." (PMID 17342087, 2007). "Our findings align with those found in HNSCC and breast cancer, as they demonstrate that higher KLK-6 expression decreases MMP-2 activity and invasion potential in PCa." (PMID 41597241, 2026). "Gene expression correlation analysis revealed that USP30 negatively correlates with the expression of stem cell markers such as MMP2, MMP9, MYC, OCT4(POU5F1), NANOG, ALDH1A3, CD133 (PROM1), EPCAM, CD24, and ITGA6 in breast cancer cohorts." (PMID 41306556, 2025). "Silibinin downregulates the expression of the key migration regulators MMP-2 and MMP-9 through the Jak2/STAT3 and MEK/ERK pathways in breast cancer." (PMID 41470858, 2025). "Similar findings have been seen in breast cancer, with DHA decreasing metalloproteases such as MMP2 and MMP9 as well as vimentin and reducing cell migration." (PMID 41009329, 2025). "MCF-7 breast cancer cells in a TGFβ-dependent EMT program exhibited an increased expression of TGF-b, matrix MMP2, and connective tissue growth factor (CTGF)." (PMID 40035822, 2025). "Expression levels of matrix metalloproteinase-2 (MMP-2) and MMP-9 can be utilized as biomarkers to assess the metastatic potential of ovarian cancer and the invasiveness of breast cancer cells." (PMID 40140925, 2025). "Lactate derived from hypoxic CAFs provides a metabolic coupling between CAFs and breast cancer cells and promotes breast cancer cell invasion by activating the TGF-β1/p38 MAPK/MMP2/9 signaling axis and facilitating mitochondrial activity in the cancer cells." (PMID 40565047, 2025). "LncRNA CARMN inhibits the expression of matrix metalloproteinase 2 (MMP2), a protease responsible for degrading the extracellular matrix, thereby impeding the EMT process in breast cancer cells." (PMID 40703656, 2025). "Among those 11 protein candidates, we found 6 proteins that are involved in the progression and development of breast cancer, those are MMP-1, MMP-2, MMP-9, MMP-12, M-phase inducer phosphatase-2 (CDC25B), and Aldose reductase." (PMID 40176865, 2025). "It is still unclear as to why the expression levels of MMP-2 and MMP-9 in HS578T-Hyg breast cancer cells and M13HS-2 and − 8 tumor hybrids remained unaltered or only moderately decreased." (PMID 40471394, 2025). "Methanolic bark extracts of neem modulate migration-related genes (ZO-1, MMP2, FAK, N-cadherin) in cervical cancer, while specific compounds such as phthalic acid and 4-ethylbenzamide show cytotoxicity in breast cancer." (PMID 41346617, 2025). "CTX inhibits the ERα/VASP signaling pathway in hormone receptor-positive breast cancer cells (MCF-7) and reduces MMP2 expression, limiting cell migration and invasion." (PMID 40364211, 2025). "When these findings are combined with the primary outcome of our mathematical model, MMP2 and MMP9 emerge as potential therapeutic targets for combating breast cancer." (PMID 40259907, 2025). "In breast cancer, STIP1 localizes extracellularly with Hsp90 to stabilize matrix metalloproteinase-2 (MMP-2)." (PMID 41369326, 2025). "Gelatinase-A or MMP-2 has been observed to be overexpressed in several types of cancer, including breast cancer." (PMID 40176865, 2025). "It was previously shown that MMP-2 and MMP-9 activity is increased by TGFβ1 treatment in a time- and dose-dependent manner in HCC1806 breast cancer cells." (PMID 40535569, 2025). "Several studies found that the inhibition of MMP-2 and MMP-9 can reduce breast cancer angiogenesis and metastasis." (PMID 40176865, 2025). "Rezaei and colleagues demonstrated that the expression levels of MMP-2 and MMP-9 were suppressed in minocycline-treated MCF-7 breast cancer cells." (PMID 40471394, 2025).
breast cancer (continued). "LRRN1 overexpression consistently downregulated the protein expression of focal adhesion kinase (FAK), matrix metalloproteinase-2 (MMP2), and matrix metalloproteinase-9 (MMP9) in both breast cancer cellines." (PMID 41458604, 2025). "MMP2 and MMP9, which catalyze the breakdown of gelatin IV, the primary component of the extracellular matrix, are the most common MMPs found in breast cancer." (PMID 40735254, 2025). "For instance, in retinoblastoma and breast cancer cells, PCB downregulates MMP2/9 via inhibition of FAK and p38, induces cell cycle arrest, and inhibits PI3K/AKT signaling." (PMID 41008632, 2025). "Among them, the gelatinases MMP-2 and MMP-9 have been widely studied as potential biomarkers in breast cancer, with their overexpression consistently correlated with poor outcomes in several types of cancer." (PMID 40943584, 2025). "CAFs-derived TGF-β drives EMT and enhances fibronectin, vimentin, MMP-2/9, SNAIL, and TWIST expression, promoting breast cancer cell motility, drug resistance, and stemness via upregulation of lncRNA HOTAIR, silencing tumor suppressor genes." (PMID 40230452, 2025). "In conclusion, several reports by our group and others demonstrate that lactate plays an important role in breast cancer motility in part through modulating EMT status, and the expression profile of cytokines, adhesion molecules, MMP-2, and nectin-4." (PMID 40507273, 2025). "The inhibitory potential of rosmarinic acid on MMP-1, MMP-2, MMP-9, and MMP-12 will limiting their ability to promote proliferation, invasiveness, angiogenesis, and metastasis of breast cancer cells." (PMID 40176865, 2025). "This is further supported by the study of Rezaei and colleagues, which demonstrated that minocycline significantly reduced the expression of MMP-2 and MMP-9 as well as the migratory activity of MCF-7 breast cancer cells." (PMID 40471394, 2025). "MMP2/7/9 and MT1-MMP appear co-expressed from the protein interaction network constructed by STRING database and are known to hold key roles in breast cancer development and progression." (PMID 41228316, 2025). "Several studies found that overexpression of MMP-2 and MMP-9 correlated with breast cancer metastasis and poor prognosis." (PMID 40176865, 2025). "One study evaluated the effect of curcumin treatment on MMP-2 and MMP-9 gene expression in a breast cancer cell line (MDA-MB-231)." (PMID 39335164, 2024). "The preceding results have exposed that LDBK, through B1R, provokes the release of MMP2 and MMP9 in breast cancer cells, which are key molecules for extracellular matrix degradation and invasion." (PMID 39519260, 2024). "The concentrations of MMP-2 and MMP-9 in breast cancer cells declined under treatment with the Les-6287, as well as the doxorubicin." (PMID 39199694, 2024). "Many studies documented that STAT-3-mediated breast cancer metastasis happens through the upregulation of MMP9 and MMP2 expression." (PMID 38673967, 2024). "The inhibition of STAT3 phosphorylation has reduced the expression of matrix metallopeptidases MMP2 and MMP9, which help enable breast cancer invasion and metastasis." (PMID 38935814, 2024). "The inhibition expression of matrix metalloproteinase as MMP-2 and MMP-9 expression levels in breast cancer tissues correlates with lymph node metastasis, tumor growth, angiogenesis, invasion, and metastasis." (PMID 38673967, 2024). "Combining the results of network pharmacology with other bioinformatics databases suggests that myrrh’s active components exert anti-cancer effects by regulating genes involved in breast cancer pathogenesis, particularly PTGS2, EGFR, ESR2, MMP2, and JUN." (PMID 39707884, 2024). "At the same time, M0 macrophages stimulated by MCF-7 exosomes upregulate the expression of MMP2 and MMP9 by activating ERK signaling in MCF-7 breast cancer cells, thereby promoting the proliferation and migration of tumor cells." (PMID 38356723, 2024).
breast cancer (continued). "Resveratrol at a concentration of up to 50 μM also inhibited both MMP-2 and MMP-9 in other breast cancer cell lines." (PMID 39335164, 2024). "The results obtained at the ELISA measurements proved that the Les-6287 compound can decrease the concentration of MMP-2, MMP-9, and ICAM-1 proteins involved in metastasis and poor prognosis in breast cancer patients." (PMID 39199694, 2024). "For this purpose, we used the Gene expression-based Outcome for Breast Cancer Online (GOBO) dataset that contains data about 1881 breast cancer patients to produce a gene set composed of PTGS2/ESR2/EGFR/JUN/ MMP2 genes’ signature." (PMID 39707884, 2024). "TGFβ stimulated genes matrix metallopeptidase 2 (MMP2), epiregulin (EREG), and vascular endothelial growth factor A (VEGFA) were also critical regulators of lung metastasis of breast cancer and correlated with the prognosis of breast cancer." (PMID 38245723, 2024). "Prior research has highlighted GATA4’s capability to reduce MMP2 and MMP3 expression in breast cancer." (PMID 38653973, 2024). "Lobie and group have shown an upregulation of MMP9 in endometrial cancer cells and an upregulation of MMP2 and MMP9 in breast cancer cells when treated with GH." (PMID 39123364, 2024). "These include PTGS2, EGFR, ESR2, MMP2, JUN, and HSP90AB1, which all revealed the highest mRNA expression level in the basal breast cancer subtype, thus proposing a potential similar engagement of these genes in the pathogenesis of the basal subtype." (PMID 39707884, 2024). "The expression of MMP-2 and MMP-9 is increased in many types of cancer, including lung cancer, breast cancer and glioma, and cervical cancer and is considered an important prognostic factor." (PMID 39274874, 2024). "Another study reported that synergizing with HOP, HSP40, and p23 potentiates the activation of HSP90α on matrix metalloproteinase-2 (MMP-2), thereby enhancing breast cancer cell invasion and migration." (PMID 38646439, 2024). "Consistently, SAMD5 overexpression markedly reduced Ki67, MMP2, and MMP9 protein levels in breast cancer cells relative to the control group." (PMID 39524172, 2024). "The concentration of matrix metalloproteinase 2 (MMP‐2) in tumor tissues exceeds that in normal tissues, which facilitates the growth, angiogenesis, invasion, and metastasis of breast cancer." (PMID 39545088, 2024). "Fisetin inhibits cell migration in mammary carcinoma by silencing the gene regulatory protein Nrf2 in the nuclear fraction, leading to reduced activity of MMP-9 and MMP-2." (PMID 38611849, 2024). "For the matrix degradome, MMP1, MMP2, MMP10 and MMP14 showed trends of progressive upregulation with increasing metastatic potential in lung fibroblasts exposed to secreted factors from breast cancer cells." (PMID 37903851, 2023). "In breast cancer MCF-7 cells, EGCG decreased the activity of MMP2 and its protein and mRNA expression levels." (PMID 36677584, 2023). "Such is the case of the sHH-Gli pathway, which, when inhibited with cyclopamine, decreases breast cancer MDA-MB-231 cells’ invasion and migration, and MMP-2 and MMP-9 concentrations." (PMID 38069210, 2023). "In HTB94 chondrosarcoma cells and breast cancer cells, resveratrol significantly suppresses the expression of Cyclin D1, c-Myc, SOX-2, MMP-2/9, and inhibits MMP-induced differentiation via the p38 kinase and JNK pathways as well as activation of Akt and STAT3." (PMID 37560476, 2023). "Lovastatin/mevinolin, present in the P. ostreatus ethanolic extract, inhibited angiogenesis and metastasis through the inhibition of MMP-2 and MMP-9 expression in the 4T1 metastatic breast cancer cell line." (PMID 37373268, 2023). "Parthenolide activates NADPH oxidase and increases ROS generation in breast cancer cells, increasing p-JNK levels while decreasing NF-κB, VEGF and MMP2/9." (PMID 37047552, 2023).